NRF1 (nuclear respiratory factor 1)
Diseases named in the same sentence as NRF1 in open-access papers (continued):
Sharing a sentence is not in itself a finding about the gene and the disease.
tumor (continued). "ESRRA, NRF1, POLG, PPARGCA1 and SIRT1 were identified to be significantly down-regulated in all of the mtDNA-depleted tumours." (PMID 30208958, 2018). "An NRF1-induced BCSC-like subset was able to form xenograft tumors in vivo, while inhibiting transcription of CXCR4 prevented xenograft tumor growth." (PMID 30486409, 2018). "When compared with wild-type control (Nrf1+/+), the expression of Nrf1 was markedly decreased in the Nrf1α−/− HEA157 cells-derived tumour tissue." (PMID 27065079, 2016). "The C3TFT gene-sets that were more highlyexpressed in the tumour tissue had common regulatory motives for various E2Fs, NRF2, ARNT, NRF1, MYC and YY1." (PMID 23009663, 2012). "It has been found in GBM that glucose transporter type 1 (GLUT1), HIF-1α, lactate dehydrogenase (LDH), and MCT4 were significantly expressed in the interior region of the tumor, whereas MCT1, C-MYC, and nuclear respiratory factor 1 (NRF1) were significantly expressed in the lateral region." (PMID 41450919, 2025). "Meanwhile, the UALCAN website showed that in TCGA-HNSCC cohorts, the expression level of NRF1 was higher in tumor tissues than in non-tumor tissues, as well as in the nodal metastasis status." (PMID 37914704, 2023). "Therefore, multiplex immunofluorescence was performed to examine the co-localization of NQO1, NRF1 and NRF2 within the tumor and TME." (PMID 36359002, 2022). "The NRF1 expression levels were significantly higher in tumour tissues than in non-tumour tissues (P < 0.0001)." (PMID 35448958, 2022). "Although NRF1 is not among the SMGs, we found that NRF1 mRNA is abundant in both tumor and normal specimens (bottom)." (PMID 32123008, 2020). "Though as a tumor promoter, Nrf2 can also, in turn, directly activate the transcriptional expression of Nrf1 to form a negative feedback loop." (PMID 30562963, 2018). "Except for few being chromatin regulators (CGBP, MBD2, and DNMT1), all of these TFs were found to have tumor suppressor functionality (BRCA1, E2F1&2&5&7, EGR1-4, FLI1, NRF1, TFDP2, and STAT1), or indirectly mediate the suppression of tumorigenesis and tumor suppressor activity (SP4 and ZBTB33)." (PMID 29740534, 2018). "Large tumor spheroids were observed by HoloMonitoring and confocal microscopy, for live images of NRF1 and NRF1+E2 BTIC clones compared to vector control did not form tumor spheroids at 5 and 15 days." (PMID 30486409, 2018). "However, treatment of Nrf1-expressing cells with 12-O-tetradecanoylphorbol-13- acetate (TPA, a tumor promotor to induce AP-1 that comprises c-Jun and c-Fos) resulted in a significant decrease in the ARE-driven reporter activity." (PMID 30261697, 2018). "Conversely, although Nrf2 is defined as a tumor promoter, it also directly mediates the transcriptional expression of Nrf1 so as to form a negative feedback loop." (PMID 30562963, 2018). "Finally, NRF1 was found to bind to and transactivate MALAT1 promoter, providing evidence of a novel regulatory loop in MM cells, whose targeting by g#5 enhanced bortezomib anti-tumor activity both in drug sensitive and resistant MM cells." (PMID 29487387, 2018). "Given the common role of NRF-1 and GABP in regulating mitochondrial function, the NRF-1 > GABPβ > BRCA1 pathway suggests a link between tumour initiation via disruption of stem cell maturation and the abnormal mitochondrial metabolism (Warburg effect) that has long been observed in tumours." (PMID 21609478, 2011). "Though no clear function of NRF1 in cancer cells has been reported, our finding that the NRF1-binding motif correlates with tumor malignancy may reflect hypermetabolism in aggressive tumors." (PMID 18823535, 2008). "Though it was not demonstrated if the oncogenic property is related to DDI2′s protease activity or an alternative, such as serving as an ubiquitin receptor protein, it is possible that a DDI2 protease inhibitor may have anti-tumor activity independent of the NRF1-mediated bounce-back response." (PMID 31947743, 2020).
tumor (continued). "Hence, we believe that regulation of NRF1 expression via SIAH2 by oxygen tension is a switch for a series of intrinsic and extrinsic cellular reactions during tumor progression, which may be of great importance for tumor maintenance." (PMID 30833558, 2019). "Individual protein analysis for NQO1, NRF1 and NRF2 and triple-negative phenotyping (NQO1−NRF1−NRF2−) failed to generate clinically-relevant high and low cut-offs, showing no significance in tumor cells." (PMID 36359002, 2022).
neurodegenerative disease (21 papers, 2014 to 2025). A disorder of the central nervous system characterized by gradual and progressive loss of neural tissue and neurologic function. "Chromatin immunoprecipitation followed by deep sequencing identified the hMOB3A gene as a target for the NRF1 (Nuclear respiratory factor 1), a transcription factor linked to neurodegenerative diseases." (PMID 31185650, 2019). "Two of the genes, MAPT and PSENEN, observed interacting with all three EE, E2 and NRF1 are associated with neurodegenerative disease." (PMID 27983596, 2016). "Three of the genes, GPR37, MAPT and PSENEN observed interacting with all three BPA, E2, and NRF1 are associated with neurodegenerative disease." (PMID 27983596, 2016). "NRF1, a master regulator of proteasome genes, plays a critical role in proteasome-mediated protein degradation, a process whose dysregulation has been implicated in neurodegenerative diseases." (PMID 41223260, 2025). "NRF1 is an essential transcription regulator of proteasomal gene expression in neurons, and disruption of NRF1 function may cause neurodegenerative disease pathogenesis." (PMID 37735974, 2024). "Nrf1 was identified as a major transcriptional regulator that connects the regulation of nuclear-encoded genes and mitochondrial biogenesis and has been implicated in the pathology of several neurodegenerative diseases." (PMID 30333037, 2018). "GPR37 gene, a common Cd/E2/NRF1 gene, is associated with neurodegenerative disease." (PMID 27983596, 2016). "Since mitochondrial dysfunction has been implicated as a possible pathway for neurodegenerative diseases, gene targets of NRF-1 directly affect brain health and may provide insight into mechanisms of these diseases." (PMID 27983596, 2016). "MAPT, a common DEHP, E2 and NRF1 target genes are associated with neurodegenerative disease." (PMID 27983596, 2016). "Many estrogen signaling pathway genes are NRF1 target genes, which may be also associated with neurodegenerative diseases." (PMID 27983596, 2016). "Future experiments using tissue- and cell-specific Nrf1 deletions will be critical in directly addressing how dysfunctional mitochondrial biogenesis contributes to the pathology and disease progression in neurodegenerative diseases." (PMID 30333037, 2018). "Three of the common E2 and NRF1 target genes, GPR37, MAPT, and PSENEN are associated with neurodegenerative disease." (PMID 27983596, 2016). "Nrf1 can mediate DHCR24 expression in the early stage of neurodegenerative diseases." (PMID 38649789, 2024). "Based on the longevity-related genes (i.e., Akt1, NRF1, parkin, and AIMP2), potentially effective therapeutics might be exploited for the rejuvenation and cure of age-associated neurodegenerative diseases." (PMID 36711211, 2022). "Nrf1 is a promising target for therapeutic intervention in neurodegenerative diseases, due to its ability to enhance proteasome activity, whereas Nrf2 controls the expression of antioxidant and detoxification enzymes and thereby protects cells from the damage induced by oxidative stress." (PMID 32316110, 2020). "We therefore suggest that increasing the activity of Nrf1 may be beneficial for human aging and treatment of various adult-onset neurodegenerative diseases." (PMID 30973820, 2019). "This study suggested that dysregulation of NRF1 and its targets may be involved in the pathogenesis of neurodegenerative diseases." (PMID 27983596, 2016). "Mutations in NRF1 targets PSEN1 and PSEN2 may also lead to the development of neurodegenerative disease." (PMID 27983596, 2016). "Therefore, activating the Nrf1/2 signaling pathway could be an attractive therapeutic target for the prevention of neurodegenerative diseases, including AD." (PMID 29867359, 2018).
infection (10 papers, 2014 to 2026). The state of being infected such as from the introduction of a foreign agent such as serum, vaccine, antigenic substance or organism. "Future studies will further characterise the role of various Nrf1 isoforms in HCV-associated infection." (PMID 40872767, 2025). "During infection, studies reported altered expression of NRF1 and/or NRF2 in viral infection with DENGV, Influenza A virus, HIV, HSV-1, EBV, SARS-CoV-2 and human T-cell leukemia virus type 1 (HTLV-1)." (PMID 34768767, 2021). "However, studies are required to fully resolve whether the metabolic reprogramming associated with NK cell activation is essential to NK cell immunity, and to elucidate the roles of NK cell-specific NRF1 and CPT1a in host immunity against infection." (PMID 38426112, 2024). "In view of the fact that ROS affect various transcription factors such as nuclear factor kappa-light-chain-enhancer of activated B cells (NF-κB) and activator protein-1 (AP-1), we identify whether DPI treatment affected the NRF1/2/TFAM signaling at 16 h after infection." (PMID 31011285, 2019). "For example, HCMV induces oxidative stress but also induces the activity of the transcription factors nuclear factor erythroid 2 related factor 1 (NRF1) and nuclear factor erythroid 2 related factor 2 (NRF2) to increase cellular resistance to oxidative stress during infection." (PMID 39772623, 2025). "Similarly, bacterial infection was shown to modulate the expression of NRF1/NRF2, such as infection with Staphylococcus aureus and Escherichia coli." (PMID 34768767, 2021). "Previously, in the liver, we found that transcription factors, NRF-1 and NRF-2, bind to consensus promoter sequences in Ogg1 suggesting this is part of larger program of mtDNA repair and mitochondrial biogenesis in response to infection." (PMID 24988481, 2014). "Our results showed that infection also enhances NRF1 expression, which may have negative effects on host cells." (PMID 36430657, 2022). "Relative to the control, NRF1 and NRF2 were increased to approximately 114.4% (p > 0.05) and 136.3% (p < 0.05) at 2 h postinfection, then gradually decreased and peaked at 16 h after infection, which were reduced to ~19.9% (p < 0.05) and 19.3% (p < 0.05), respectively." (PMID 31011285, 2019).
metabolic disorders (6 papers, 2020 to 2025). "Based on these insights, it is plausible to consider that NRF1 activators may be potentially used to treat certain diseases associated with proteostasis dysfunction, including neurodegeneration and metabolic diseases, by augmenting the two protein quality control systems." (PMID 37658135, 2023). "A decrease in PGC-1α expression can lead to increased levels of ROS and diminished expression of transcription factors, including NRF1, resulting in various metabolic disorders and reproductive diseases." (PMID 40565373, 2025). "Therefore, we suggest that EMPA ameliorates MASLD via NRF1, advancing our understanding of metabolic diseases." (PMID 40362294, 2025). "Meanwhile, following EMPA treatment, Nrf1 upregulation enhanced SIRT7 signaling pathway activation, protected against lipid deposition-related metabolic disorders, and inhibited lipogenesis and oxidative stress." (PMID 40362294, 2025). "Indeed, investigating the relationship between NRF1 and SIRT7 is essential for understanding metabolic diseases and developing potential treatments for obesity and T2DM." (PMID 40362294, 2025).
neurological disorders (3 papers, 2018 to 2025). "Mice carrying a central nervous system-specific deletion of Nfe2l1, the gene encoding Nrf1, display similar neurological disorders as the ones observed in sMaf-deficient mice, indicating that Nrf1 and the sMaf proteins likely collaborate in maintaining neuronal homeostasis." (PMID 28899199, 2018). "Although not in the context of neurological disorders, resveratrol's ability to increase NRF-1 levels and improve mitochondrial content has also been confirmed in human umbilical vein endothelial cells, where resveratrol overcomes diesel exhaust particulate extracts-induced inhibition of NRF-1." (PMID 36237161, 2023).
inflammation (2 papers, 2021 to 2024). Aberrant reaction of the microcirculation characterized by movement of fluid and leukocytes from the blood into extravascular tissues. "Our results show hepatic Nrf1 is important for preventing MASH-linked hepatocyte proliferation, liver inflammation, and HCC, that actions by Nrf1 and Nrf2 synergistically reduce hepatic lipid storage, and that the Nrf2-inducing drug bardoxolone alleviates liver inflammation and fibrosis." (PMID 39125617, 2024).
kidney disease (2 papers, 2022 to 2025). "While NRF1 (nuclear respiratory factor) motifs, which usually activate genes for OXPHOS system and essential for mitochondrial biogenesis, is enriched in Ureteral ATAC peaks, that emphasize the importance of regulation of mitochondrial related genes in kidney disease." (PMID 40034749, 2025).
brain disease (1 paper, 2016). "This suggests that NRF1 is actively involved in the regulation of glutamatergic synaptic transmission in neurons and also possibly in brain diseases." (PMID 27983596, 2016). "Many genes modified by EEDs are common targets of both (E2) and NRF1 and some of these genes are involved with the specified brain diseases." (PMID 27983596, 2016). "Therefore, NRF1 is an emerging potential target for therapeutic intervention for brain diseases, including AD." (PMID 27983596, 2016).
NRF1 also shares sentences with these, for which no sentence is quoted: hematologic malignancies (3 papers); adenocarcinoma (2); atherosclerosis (2); cardiovascular disease (2); diffuse large B-cell lymphoma (2); dyslipidemia (2); fragile X mental retardation syndrome (2); Parkinson's (2); skin cancer (2); age-related macular degeneration (1); autism (1); autism spectrum disorder (1); bladder cancer (1); bladder urothelial carcinoma (1); brain neoplasm (1); Burkitt lymphoma (1); carnosinase deficiency (1); cerebral edema (1); chronic myelogenous leukemia (1); colon adenocarcinoma (1); colorectal adenocarcinoma (1); colorectal tumor (1); COVID-19 (1); diabetic cardiomyopathy (1); diabetic neuropathy (1); dwarfism (1); dysplastic (1); endothelial dysfunction (1); eosinophilia (1); glucose metabolic disorder (1).
A further 32 diseases each share a sentence with NRF1 in 1 paper.